OR56A3 (olfactory receptor family 56 subfamily A member 3)
Description:
Odorant receptor.
Synonyms: OR56A3P; OR56A6; OR56A2P
Tractability: Antibody: UniProt places it where antibodies can reach, with medium confidence; UniProt predicts a signal peptide or a membrane-spanning region; its Gene Ontology location is reachable by antibodies, with medium confidence.
Gene: Protein-coding gene on chromosome 11 (5,938,751 to 5,951,347, forward strand). Ensembl gene ENSG00000184478.
Subcellular location: Cell membrane
Pathways (Reactome):
Sensory Perception: Expression and translocation of olfactory receptors
Gene Ontology:
Molecular function: olfactory receptor activity; G protein-coupled receptor activity; signaling receptor activity
Biological process: cellular response to lipid; detection of chemical stimulus involved in sensory perception of smell; G protein-coupled receptor signaling pathway; system process
Cellular component: plasma membrane; membrane
Genetic constraint (gnomAD): Loss-of-function variants: 23 observed, 18.41 expected, observed/expected ratio (o/e) 1.25, 90% interval 0.9 to 1.74. The upper end of that interval is the gene's LOEUF score, 1.74, which puts it in group 6 of 6, group 1 being the genes least tolerant of losing a copy. Missense variants: 366 observed, 397.84 expected, observed/expected ratio (o/e) 0.92, 90% interval 0.84 to 1. Synonymous variants: 172 observed, 154.81 expected, observed/expected ratio (o/e) 1.11, 90% interval 0.98 to 1.26.
Homologues: Orthologues: chimpanzee OR56A3 (99% identical), rat Or56a3b (86% identical), mouse Or56a3 (85% identical), mouse Or56a3b (85% identical), rabbit OR56A3 (85% identical), dog OR56A3C (83% identical), dog OR56A3D (83% identical), dog OR56A3E (83% identical), zebrafish adra1ab (18% identical), Caenorhabditis elegans ser-5 (17% identical), zebrafish adra2da (15% identical), zebrafish adra2db (14% identical). Paralogues in human: OR56A1 (77% identical), OR56A4 (75% identical), OR56A5 (71% identical), OR13F1 (30% identical), OR5T1 (29% identical), OR5T3 (28% identical), OR5T2 (26% identical), ADRA1A (18% identical), ADRB3 (18% identical), ADRA1B (18% identical), ADRB1 (17% identical), DRD2 (17% identical), and 6 more.
Diseases named in the same sentence as OR56A3 in open-access papers:
OR56A3 is named in the same sentence as 1 disease in open-access papers, as found by Europe PMC text mining. Sharing a sentence is not in itself a finding about the gene and the disease.
OR56A3 shares sentences with these, for which no sentence is quoted: breast carcinoma (1 paper).